ECHS1 (enoyl-CoA hydratase, short chain 1)
Diseases named in the same sentence as ECHS1 in open-access papers (continued):
Sharing a sentence is not in itself a finding about the gene and the disease.
cardiac hypertrophy (2 papers, 2021 to 2024). "By constructing ECHS1 knockout mice, it was found that ECHS1 homozygous knockout mice produced embryo death, and heterozygous defective mice significantly promoted the occurrence of myocardial hypertrophy under the stimulation of angiotensin II." (PMID 38331935, 2024). "In human cardiac hypertrophy, short-chain enoyl-CoA hydratase (ECHS1) was reduced, which was coupled with elevated H3K18cr and H2BK12cr." (PMID 34262024, 2021). "On the contrary, cardiomyocyte-specific overexpression of ECHS1 could protect against the occurrence of myocardial hypertrophy." (PMID 38331935, 2024).
colon cancer (2 papers, 2017 to 2021). "Our model is echoed by our findings that, in cancers such as RCCs, HCCs and colon cancers, which originated from metabolic organs that are exposed to nutrients, ECHS1 is severely downregulated." (PMID 28878358, 2017).
hypertrophic cardiomyopathy (2 papers, 2021 to 2024). A condition in which the myocardium is hypertrophied without an obvious cause. "Therefore, histone crotonylation may serve as a therapeutic target for children with ECHS1 mutations and patients with hypertrophic cardiomyopathy." (PMID 39606030, 2024). "Recently, downregulation of short-chain enoyl-CoA hydratase (ECHS1) was showed in human hearts with hypertrophic cardiomyopathy." (PMID 34512158, 2021).
Leukoencephalopathy (2 papers, 2018 to 2020). This term describes abnormality of the white matter of the cerebrum resulting from damage to the myelin sheaths of nerve cells. "Further papers described ECHS1 mutations variously associated with vacuolating leukoencephalopathy, basal ganglia abnormalities or a slow neurodegenerative condition with global brain atrophy or a single episode of metabolic acidosis." (PMID 30029642, 2018).
microcephaly (2 papers, 2021 to 2022). A congenital or acquired developmental disorder in which the circumference of the head is smaller than normal for the person's age and sex. "In ECHS1 deficiency patients, microcephaly and impaired vision are usually detected by physical examination." (PMID 36064416, 2022). "ECHS1 deficiency is also linked with the occurrence of pachygyria, microcephaly and dysmorphic facies." (PMID 34256807, 2021).
overnutrition (2 papers, 2017 to 2019). An imbalanced nutritional status resulting from excessive intake of nutrients. "Overnutrition suppressed enoyl-CoA hydratase-1 (ECHS1) activity and linked to increased risk of cancer." (PMID 31258820, 2019). "Together, alternative anticancer measures may be possible for overnutrition and its associated metabolic diseases by activating ECHS1." (PMID 28878358, 2017). "Therefore, whether and how ECHS1 regulates FAs and BCAAs catabolism and cellular FAs and BCAAs levels is of importance in efforts to understand the tumorigenic impact of overnutrition." (PMID 28878358, 2017).
renal carcinoma (2 papers, 2022 to 2025). A carcinoma arising from the epithelium of the renal parenchyma or the renal pelvis. "Finally, we identify early dysregulated genes (e.g., FBP1, CCDC8, ECHS1, CLDN7) and pathways in renal cancer, often related to metabolism (e.g., pentose phosphate pathway)." (PMID 41188181, 2025). "AMPK in renal cancer cells, a sensor of nutrient deprivation and metabolic stress, is inactivated in the AMPK-GATA3-ECHS1 signaling pathway, inhibiting the expression of the transcription factor GATA3 and leading to a decrease in the synthesis of ECHS1." (PMID 35251009, 2022).
renal cell carcinoma (2 papers, 2017 to 2024). "However, in renal cell carcinoma 12, 13, the ECHS1 expression is significantly alleviated than in adjacent tissues and can inhibit tumor cell proliferation." (PMID 38169583, 2024). "However, in renal cell carcinoma 12, 13, ECHS1 expression is substantially downregulated and could inhibit tumor cell growth." (PMID 38169583, 2024).
viral infection (2 papers, 2022). "ECHS1 deficiency symptoms may be exacerbated during illnesses such as viral infections, as happened in our case." (PMID 35206276, 2022).
Anxiety (1 paper, 2021). Intense feelings of nervousness, tension, or panic often arise in response to interpersonal stresses. "In addition, a reduced level of Uqcrb in both the depression-susceptible and anxiety-susceptible groups, and elevated levels of Echs1 and Hspa8 in both the anxiety-susceptible and insusceptible groups were found as compared to the control group." (PMID 33737865, 2021).
Arrhythmia (1 paper, 2021). Any cardiac rhythm other than the normal sinus rhythm. "When the 90 node genes were compared with the arrhythmia-related targets, 40 (95.2% of 42) overlapping genes were assigned, with the other two non-overlapping genes being SLC22A5 and ECHS1." (PMID 35004871, 2021).
central obesity (1 paper, 2011). "The minor G-allele of rs11101721 in ECHS1 associated with central obesity (ORadd = 1.21(1.05–1.40), Padd = 0.008)." (PMID 21339799, 2011).
central precocious puberty (1 paper, 2021). "Our data showed the down-regulation of ECHS1 that suggested the identification of ECHS1 mutation and the detection of lactic acid changes maybe valuable in specific central precocious puberty patients." (PMID 34748517, 2021).
deficiencies (1 paper, 2023). "In the case of ECHS1 and HIBCH genes, encoding a hydratase and a hydrolase enzyme, respectively, in the final valine metabolism, LSS is the most common clinical manifestation of these genetic deficiencies." (PMID 37628588, 2023).
dementia (1 paper, 2020). Loss of intellectual abilities interfering with an individual's social and occupational functions. "ACSL4, ECHS1, and HSP90B1 have no reported association with AD or related dementias, however, which suggests that our study has the potential to identify new targets in the molecular pathogenesis of this disease." (PMID 33116184, 2020).
dyslipidemia (1 paper, 2011). "PPARα agonists used to treat dyslipidemia have been shown to moderately induce the expression of ACADL and ECHS1 in rat liver, and in rat heart muscle PPARα agonists increase the expression of ECHS1 and reduce the expression of HADHA/B." (PMID 21339799, 2011).
Glomerular sclerosis (1 paper, 2025). Accumulation of scar tissue within the glomerulus. "Therefore, ECHS1 may be a potential therapeutic target for glomerular sclerosis and renal fibrosis." (PMID 40063869, 2025). "ECHS1 may protect against myocardial damage caused by doxorubicin.However, no study has investigated the correlation between ECHS1 and glomerular sclerosis." (PMID 40063869, 2025).
hepatitis B virus infection (1 paper, 2021). A viral infection caused by the hepatitis B virus. "In the absence of hepatitis B virus infection, the ECHS1 gene was subjected to RNA interference and was found to promote apoptosis after transfection into HepG2 cells." (PMID 33602268, 2021). "The results of this study are consistent with those obtained after RNA interference in the absence of hepatitis B virus infection, indicating that not all viruses can use ECHS1 as a binding protein for viral surface antigens, thereby promoting apoptosis." (PMID 33602268, 2021).
Intellectual disability (1 paper, 2015). "This patient was investigated in the context of an intellectual disability study but the relevance of the ECHS1 variants was hitherto unclear." (PMID 26000322, 2015).
latent infection (1 paper, 2023). "In the present study, the up-regulated ECHS1 may be an important host receptor of invading parasites, and associated with the inhibition of parasites self-glucose metabolism, thereby promoting the formation of intracellular bradyzoites and establish long-term latent infection in the host." (PMID 37721957, 2023).
lipid metabolism disorders (1 paper, 2025). "In this study, seven core genes (Amacr, Cyp39a1, Echs1, Gpd2, Osbpl9, Acsl4, and Mcee) closely associated with lipid metabolism disorders in AP were systematically identified through the integration of bioinformatics and machine learning approaches." (PMID 41007695, 2025).
lymph node metastasis (1 paper, 2024). "Additionally, deeply invaded GC tumor tissues (T3-4), lymph node metastasis (LNM), and advanced tumor-node-metastasis (TNM) stage (III-IV) indicated enhanced ECHS1 levels than in T1-2 (P < 0.01), without LNM (P < 0.05), and with TNM stage I-II (P < 0.001), respectively." (PMID 38169583, 2024).
metastatic melanoma (1 paper, 2023). A melanoma that has spread from its primary site to another anatomic site. "The ECHS1 gene, crucial for fatty acid beta-oxidation, interacts with STAT3 and has been linked to metastatic melanoma." (PMID 37844995, 2023).
neuroaxonal dystrophy (1 paper, 2021). A nonspecific term referring both to the pathologic finding of swelling of distal portions of axons in the brain and to disorders which feature this finding. "PLA2G6 and ECHS1 gene sequence analysis was performed to rule out infantile neuroaxonal dystrophy (INAD) and bilateral striatal necrosis, respectively." (PMID 34246313, 2021).
neuroblastoma (1 paper, 2020). Neuroblastoma (NB) is the most common solid, extracranial childhood tumor. "The experiment was repeated in human neuroblastoma SHSY5Y cells after ECHS1‐downregulation obtained by transient RNA interference and confirmed at protein level (30% compared to mock‐transfected cells)." (PMID 32329585, 2020).
pyruvate dehydrogenase deficiency (1 paper, 2022). A rare neurometabolic disorder characterized by a wide range of clinical signs with metabolic and neurological components of varying severity. "ECHS1 deficiency, for instance, can cause secondary pyruvate dehydrogenase deficiency, resulting in clinical symptoms." (PMID 36188600, 2022).
SCAD deficiency (1 paper, 2015). "Palmitate loading in fibroblasts of three ECHS1 patients induced an acylcarnitine profile very similar to that of short-chain acyl-CoA dehydrogenase (SCAD) deficiency." (PMID 26000322, 2015).
ureter transitional cell carcinoma (1 paper, 2017). A carcinoma that arises from the transitional epithelium of the ureter. "However, the change in the levels of ECHS1 were much more moderate in cancers such as prostate or ureter transitional cell carcinoma than in the cancers derived from metabolic organs." (PMID 28878358, 2017).
cancer (15 papers, 2013 to 2025). A tumor composed of atypical neoplastic, often pleomorphic cells that invade other tissues. "Furthermore, elevated expression of HADH and ECHS1 has been significantly associated with cancer progression and adverse clinical outcomes across various malignancies, which aligns with the results of this study." (PMID 41573739, 2025). "Additionally, ECHS1 is linked with the development of different tumors and induces cancer malignancy by lipid metabolism remodeling and intercellular oncogenic signaling pathways modulation." (PMID 38169583, 2024). "Most importantly, in addition to abnormal FA-oxidation (FAO) synthesis, the relevance of phospholipid metabolism associated with ECHS1 and cancer-cell function is unknown." (PMID 34615856, 2021). "Compared to normal cells which depend on nutrient signals to inactivate ECHS1 and to trigger the anabolic metabolism, cancer cells may trigger anabolic metabolism by gaining mTOR activating mutations or ECHS1 inactivating mutations." (PMID 28878358, 2017). "Subsequent studies revealed that ECHS1 exerts oncogenic or tumor-suppressive effects by mediating metabolic reprogramming in multiple cancers, as evidenced by its aberrant expression." (PMID 40063869, 2025). "We found that GCDH was upregulated and had an inverse pattern of expression with the downstream enzyme ECHS1 (Enoyl Coenzyme A hydratase, short chain 1) in TCGA cancer vs. normal tissue dataset." (PMID 40810390, 2025). "In these cancer cells, enoyl-CoA hydratase-1 (ECHS1), a key enzyme in BCAA metabolism, is downregulated." (PMID 40437561, 2025). "In most cancers, the expression of ECHS1 is upregulated, including in non–small cell lung cancer, pancreatic cancer, and colon cancer." (PMID 39328412, 2024). "Short-chain enoyl-CoA hydratase (ECHS1) exerts pro- or anti-cancer activities in different cancer backgrounds." (PMID 38169583, 2024). "The mTOR signaling pathway, as a classic targeted molecule for the systemic therapy of RCC, has also been shown to promote and regulate the proliferation and invasion of cancer cells and is regulated by ECHS1, a key enzyme in fatty acid metabolism." (PMID 36591111, 2022). "It was reported that the expression of ECHS1 was significantly increased in colorectal, liver, and gastric cancers." (PMID 34615856, 2021). "The expression of ECHS1 has been identified in numerous types of cancer cells or patient tissues by gene or proteomic expression profiling." (PMID 34615856, 2021). "Other genes, such as CALCOCO2, RCAN2, ADI1, ECHS1, PLOD1 and VTI1B were associated with tumorigenesis or angiogenesis in some other cancers 33-35." (PMID 31632497, 2019). "Consistent with this prediction, western blot assays for affinity-purified endogenous ECHS1 found that ECHS1 from cancer tissue was acetylated to a greater degree than was normal adjacent tissues corresponding to the tumor." (PMID 28878358, 2017). "As a result of this testing the two of these SNPs rs7894051 (in ECHS1 gene), and rs4904670 (in NRDE2 gene) were selected for further analyses of their associations with major diseases (cancer and CHD) and physiological aging changes." (PMID 25918517, 2015). "Some of these proteins, including Rpl21, Atic, Eif3s2, Echs1, Eps15 and Ywhab, have previously been reported to be involved in cancer genesis and progression." (PMID 23895178, 2013). "Furthermore, ECHS1 has a potential clinical application prospect in diagnosing and prognosis of malignant tumors." (PMID 38169583, 2024). "Apart from its critical roles in regulating fatty acid metabolism, numerous literatures have indicated that ECHS1 might be involved in the development of tumor, including colon, liver, gastric, and renal cancer." (PMID 34615856, 2021). "In the current study, we investigated whether, and just how nutrients coordinate FAs and BCAAs oxidation through ECHS1 acetylation, and how this regulation promotes the initiation of cancer." (PMID 28878358, 2017).
cancer (continued). "Prolonged inactivation of ECHS1 such as constant exposure to nutrients; however, may result in cancer initiation." (PMID 28878358, 2017). "Thus, ECHS1 levels in cancer cells derived from metabolic organs are more sensitive to nutrient regulation than are other carcinomas." (PMID 28878358, 2017). "Furthermore, it has been indicated that ECHS1 can be utilized for early diagnosis and prognosis, suggesting that it could be a potential index for early diagnosis and cancer prognostic." (PMID 38169583, 2024). "Simultaneously, ECHS1 tends to interact with the SH3 domain at the C terminus of LASP1 to stimulate ceramide metabolism and cancer aggressiveness." (PMID 34615856, 2021). "Severely decreased ECHS1, accumulation of BCAAs and FAs, activation of mTOR and overexpression of BCL-2 were observed in cancer tissues from metabolic organs." (PMID 28878358, 2017). "The western blot analyses indicated that the expression levels of ECHS1, but not other analyzed β-oxidative enzymes, were severely decreased in all three cancers." (PMID 28878358, 2017). "As metabolic organs are directly exposed to high levels of glucose and other nutrients, we predicted that hyperacetylated and inactivated ECHS1 accumulated BCAAs and FAs; therefore, increased BCL-2 expression would be observed in cancers originating from these organs." (PMID 28878358, 2017).
tumor (14 papers, 2017 to 2025). "These research studies indicate that ECHS1 is essentially linked with the development of tumors, but its expression is characterized by tumor heterogeneity." (PMID 38169583, 2024). "It was indicated that increased ECHS1 expression was markedly linked with tumor location (P = 0.002), tumor invasion depth (P = 0.007), LNM (P = 0.021), and TNM stage (P = 0.001)." (PMID 38169583, 2024). "Although evidence suggests a potential role of ECHS1 involved in tumor occurrence and development, the underlying mechanisms have not been elucidated to date." (PMID 34615856, 2021). "Our findings elucidate the pivotal roles of BCAAs and ECHS1 in modulating tumor growth and highlight potential targets for therapeutic intervention." (PMID 40437561, 2025). "A subsequent correlation analysis between these genes in normal and GC tissues showed a robust correlation for the ECHS1 gene in tumor tissues, which was in stark contrast to the weak correlation observed in normal tissues." (PMID 39328412, 2024). "This investigation further confirmed the upregulation of mRNA and protein ECHS1 levels in GC tumor tissues." (PMID 38169583, 2024). "In conclusion, this investigation indicated upregulation of ECHS1 in GC tumor tissues, which was associated with tumor location, TNM stage, tumor invasion depth, LNM, and poor survivals." (PMID 38169583, 2024). "ECHS1 plays an important role in phospholipid metabolism, tumor occurrence, development, and drug resistance." (PMID 37138869, 2023). "In this study, we first found that LASP1 is related to the metabolism of phospholipids, especially ceramides, in tumor cells, and regulates the lipid-metabolism enzyme ECHS1." (PMID 34615856, 2021). "Meanwhile, along with the increase in ECHS1 expression, the number of Ki-67-positive tumor cells significantly increased in tumors." (PMID 34615856, 2021). "Furthermore, it was observed that increased ECHS1 was markedly linked with GC TNM stage, tumor location, tumor invasion depth, and LNM." (PMID 38169583, 2024). "In addition to participating in lipid metabolism, ECHS1 is also crucial for various tumor development." (PMID 38169583, 2024). "Furthermore, IHC also revealed that 42.86% (33/77) GC tissue samples had enhanced staining of ECHS1, whereas high ECHS1 signals were observed in 62.34% (48/77) of tumor-adjacent specimens, which further confirmed that ECHS1 was upregulated in GC tumor tissues." (PMID 38169583, 2024). "Overexpression of ECHS1 could promote tumor-cell invasion, migration, and proliferation of CRC cells in vitro and in vivo." (PMID 34615856, 2021). "Furthermore, in vivo subcutaneous tumor formation in BALB/C nude mice was significantly increased in the ECHS1-overexpressing groups compared with the control groups after the injection of Oxaliplatin (1.5 mg/kg)." (PMID 34615856, 2021). "The inhibition of the expression of either gene could impair tumor cell proliferation, induce apoptosis, and alter the gene expression level of tryptophan metabolism, indicating that ECHS1- and HADH-driven amino acid metabolism may contribute to tumor development." (PMID 41573739, 2025). "In addition, ALDH2 and ECHS1 may serve as novel tumor markers, providing a foundational basis for inhibiting GC progression." (PMID 39328412, 2024). "Moreover, ECHS1 knockdown in HepG2 and ACHN cells both resulted in facilitated tumor xenografts growth in mice, and putting back K/Q mutant into ECHS1 knockdown HepG2 and ACHN cells resulted in faster tumor xenografts growth than those of putting back the wild type and K/R mutant." (PMID 28878358, 2017). "ECHS1 expression was notably reduced in tumor tissues, whereas GCDH, YEATS2, H3K27cr, and Twist1 exhibited increased staining intensity in tumor sections compared to the adjacent normal tissues." (PMID 40810390, 2025).